CD4 (CD4 molecule)
Diseases named in the same sentence as CD4 in open-access papers (continued):
Sharing a sentence is not in itself a finding about the gene and the disease.
tumor (continued). "Using flow cytometry, we found out that the frequencies of CD3+CD4+ lymphocytes, B cells, and natural killers (NKs) were not significantly different between the two genotypes in both spleen and tumor stroma." (PMID 34041030, 2021). "This suggested that the anti-cancer impact of high salt activated wild-type CD4+T cells is not due to enhanced tumor localization." (PMID 33918403, 2021). "Interestingly, in sunitinib-treated mice, there is a higher infiltration of CD4+ and CD8+ within the tumor with a lower CTLA-4 and PD-1 expression, preventing T cells exhaustion." (PMID 34064508, 2021). "Moreover, we observed an increase in the tumor-infiltrating CD4+ T cells and CD8+ T cells from low-dose TSA treated tumor-bearing mice compared to control group." (PMID 33564072, 2021). "High levels of CD4 and CD8 cell infiltration may achieve partial elimination or equilibrium in these tumours, resulting in longer DFS." (PMID 33481339, 2021). "We did not observe significant differences in the tumor growth and tumor weights between Cdk6fl/fl CD4-Cre and Cdk6fl/fl mice." (PMID 34248938, 2021). "Additionally, we assessed the infiltration of CD4+ and CD8+ T lymphocytes in the tumor microenvironment." (PMID 34947972, 2021). "Through in-depth immunological mechanistic studies we found that cryo-thermal therapy induced Th1-dominant CD4+ T cell differentiation and downregulated the proportion of Tregs in B16F10 melanoma models, which facilitated tumor-specific and robust immune protection." (PMID 34576115, 2021). "Meanwhile, blockade of the TGF-βR axis using the specific inhibitors could largely protect CD8+ and CD4+ ROR1-CAR-T cells from the suppressive impacts of TGF-β, facilitating their tumor-suppressive activity in the 3D tumor model." (PMID 34321099, 2021). "Moreover, this combination appears to skew the CD4+/CD8+ T cell ratio in favor of CD8+ T cells, in line with our previous observation that the efficacy of this combination is dependent on tumor-specific CD8+ T cells." (PMID 34575546, 2021). "We present a retrospective study with TMA analysis, to explore the correlations of TILs (CD3+, CD8+, or CD4+) with clinical characteristics and blood indicators in HGSOC; based on which novel nomograms to help monitor the density levels of TILs in the tumor environment were developed." (PMID 33718143, 2021). "Additionally, we performed immunohistochemical staining for SOX10, CD3, CD4, CD8, BCL2, and caspase-3 in lgCMN tissues to detect the tumor-infiltrating lymphocytes (TILs) and antiapoptotic phenomenon." (PMID 34912899, 2021). "Taken together these results show that combination treatment of a protein vaccine and a STINGa promotes both intra-tumoral infiltration of antigen-specific effector CD8 T cells and the functionality of peripheral CD4 T cells, resulting in the inhibition of B16-OVA tumor growth." (PMID 34276686, 2021). "The expression level of ACADSB was positively correlated with tumor purity and the infiltration levels of CD4+ T cells, dendritic cells, and neutrophil, but not with the infiltration levels of CD8+ T cells, B cells, and dendritic cells." (PMID 34868460, 2021). "Tregs are a group of tumor-infiltrating immunosuppressive CD4+ T cells that mainly rely on FAO rather than glycolysis." (PMID 34742349, 2021). "Interestingly, the percentage of Tregs (CD4+Foxp3+) was upregulated in the RFA and cryo-thermal treated groups compared with the tumor-bearing mice, and the proportion of Tregs in the cryo-thermal treated group was much higher than that in the RFA group." (PMID 34576115, 2021). "For example, anti-G-CSF treatment could also induce anti-tumor immunity through the activation of NK cells, IL12-producing macrophages, as well as CD4+ and CD8+ T cells in a CRC mouse model." (PMID 34248142, 2021).
tumor (continued). "The IL2RB-biased engineered cytokine NKTR-214 significantly increases the ratio of CD8 CTLs to immunosuppressive CD4 FOXP3 T-regulatory cells, creating a potent anti-tumor environment, while also increasing the expression of immune-checkpoints such as CD274 (PDL1)." (PMID 33928242, 2021). "The anti-tumor effects of imatinib are reduced in the setting of depleted CD8 + but not CD4 + T cells, natural killer (NK) cells or myeloid cells." (PMID 33402214, 2021). "Tumor tissues were immunohistochemically analyzed for the expression of Ki67, CD45, CD4, CD8, PD1, PD-L1, PD-L2 and CD34, by Nanostring nCounter PanCancer Immune Profiling Panel as well as a comprehensive methylome profiling using the Infinium MethylationEPIC BeadChip." (PMID 33953302, 2021). "However, the indices of tumor cell proliferation inhibition (CD3, CD4, CD4/CD8, IgM, IgA, IgG, and C4) were significantly improved after 6 months of SHD treatment, and CD4/CD8 had improved compared with the control group." (PMID 34485118, 2021). "Conversely, CD4+ and CD8+ T-cells were activated within the tumor." (PMID 34503272, 2021). "Of interest, CD4 positive and CD8 positive T cells of CD200high NB were shown to produce less interferon gamma and tumor necrosis factor alpha thereby inhibiting anti-tumor immunity." (PMID 34026614, 2021). "Second, we only analyzed serum CD4+ and CD8+ T cells, although immune cells may play different roles and prognoses in the tumor microenvironment." (PMID 34692475, 2021). "Results showed that most immune cells in tumor microenvironment including CD8+ T cells, CD4+ T cells, monocytes, B cells, dendritic cells, and NKT cells were negatively associated with the high-risk scores, whereas fibroblasts hold distinct results in different algorithms." (PMID 35083132, 2021). "Tregs, in a CTLA-4-dependent manner, inhibit proliferation of CD4+ and CD8+ T cells and downregulate the expression of co-stimulatory molecules (CD80 and CD86) on DCs, attenuating their capacity for induction of effective anti-tumour immunity." (PMID 34299373, 2021). "Of note, the CD8/CD4 and CD8/CD4 Foxp3 ratios remained unchanged, likely reflecting a non-selective increase in lymphocyte tumor infiltration upon TSP1 knockdown." (PMID 34439212, 2021). "Previous studies revealed that immune evasion is mainly resulted from immunosuppression microenvironment and tumor immunoediting, which make tumor cells to escape from immune destruction of CD8 cytotoxic T lymphocytes (CTLs), CD4 Th1 helper T cells or natural killer (NK) cells." (PMID 33407498, 2021). "Interestingly, C108 not only increased the infiltration of CD45+ immune cells, but also increased the number of functional cytotoxic tumor‐infiltrating CD8+ T cells and CD4+ T cells in MCa‐PSTC model by flow cytometry." (PMID 33525064, 2021). "The levels of CD4+ T-cells infiltrating the tumor were low and no different than levels observed in the control for mice immunized with CDC25B or COX2 peptides (p>0.55 for both)." (PMID 34526999, 2021). "We performed a systematic review of RCTs to assess HPV vaccines efficacy and safety on HIV-infected people compared to placebo or no intervention in terms of seroconversion, infections, neoplasms, adverse events, CD4+ T-cell count and HIV viral load." (PMID 33654181, 2021). "Moreover, huFLT3L treatment was associated with significantly increased proliferation (Ki-67+ staining) of OVA-specific CD4 and CD8 T cells in tumor-draining lymph nodes and spleen." (PMID 34083417, 2021). "Significant associations with CRC prognosis were observed for CD4+ T cells, CD8+ T cells, B cells, NK cells, and lymphocytes, independent of age, sex, tumor stage, tumor subsite, and therapy." (PMID 34204621, 2021). "Compared with tumor-bearing DCs, cryo-thermal DCs increased the percentage of Th1, Th2 and Th17 subsets but did not affect the differentiation of CD4 CTL, Tfh, or Tregs." (PMID 34209797, 2021).
tumor (continued). "Immunohistochemical staining for CD4+ and CD8+ T cells showed remarkably increased numbers of CD4+ and CD8+ T cells infiltrating into MBT-2 tumor tissues in mice treated with the combination of B. longum 420 and following anti-PD-1 antibody compared to the other treatment groups." (PMID 34589578, 2021). "Altogether, these results suggest that NK, CD4+ and CD8+ cells may all contribute to the anti-tumor effect of VTX + CTX." (PMID 33452311, 2021). "The fresh cells analysis of the tumor microenvironment in patients exposed to anti-PD-1 found CD8+ lymphocyte depletion, with an elevated CD4+/CD8+ lymphocytes ratio (median ratio 9.77 in exposed anti-PD-1 versus 2.39 in not-exposed anti-PD-1 patients; p = 0.0943)." (PMID 34771650, 2021). "The anti-tumoral effect was correlated with the generation of CD4+, CD8+ T cells, and CD44+ CD62L- CCR7low CD127low T-effector memory cells, and the reduction of CD4+ CD25+FoxP3+ Tregs, Arg1+ CD11b+ Gr1+, and Arg1+ and CD11b+ Ly6+ myeloid-derived suppressor cell populations within the tumor." (PMID 34957134, 2021). "The expression level of STAR was positively correlated with the infiltration levels of CD4+ T cells, but not with tumor purity and the infiltration levels of CD8+ T cells, dendritic cells, B cells, macrophages, and neutrophil." (PMID 34868460, 2021). "Consistent with the hypothesis of UDP acting as an activator of anti-tumor immune response, we also found that in UDP-treated tumors the percentage of TILs CD3+CD8+ and CD3+CD4+ were increased." (PMID 34604232, 2021). "cDC1 plays an important role in eliciting an anti-tumor CD8+ T cell response mediated by MHC-I and supports T cell effector functions by releasing IL-12, while cDC2 appears to be involved in the activation of CD4+ T cells mediated by MHC-II." (PMID 33413697, 2021). "And specific-gene signature of other clusters, such as CD4+ cluster and CD8+-T/NKT/NK cluster did not yield significant survival association, which is not consistent with perception of T/NK cell anti-tumor function." (PMID 33648605, 2021). "They stimulate a CD4+ T cell-dependent delayed-type hypersensitivity reaction, promote robust CD4+ and CD8+ T cell proliferation, and elicit CD8+ T cell-dependent target cell killing and anti-tumor immunity." (PMID 34373452, 2021). "Interestingly, we demonstrated a significant CD4+ and CD8+ gradient across intra- and peri-tumoural areas, suggesting T-cell restriction to the periphery of the tumour." (PMID 33946676, 2021). "All patients exhibited both CD4+ and CD8+ responses and longitudinal tracking showed that these cells persisted and that the neoantigen-specific repertoire broadened over time, suggesting a profound repolarization of the tumour microenvironment." (PMID 34439399, 2021). "We found that the expression of FOXP3 and CCR4, and the percentage of CD4+FOXP3+ and FOXP3+CCR4+ Tregs chemoattracted to the tumor sites were significantly downregulated in the shL1CAM group, but upregulated in the L1CAM overexpression group, as compared with the control." (PMID 33710805, 2021). "Cell therapy with retrovirally transduced CD4+ T cells expressing a TCR specific-for-another-cancer-testis antigen, MAGE-A3, presented by HLA-DPB1*0401 also led to partial and complete response across several tumor types." (PMID 34910940, 2021). "In addition to cDC1s, which orchestrate the cross-talk between CD4 and CD8 T cells to achieve a potent T cell response, plasmacytoid dendritic cells (pDCs) are emerging as important regulators of anti-tumor responses." (PMID 34290401, 2021). "We speculated that the occurrence and progression of HCC promoted by enhanced CENPL may be partly attributed to augmenting tumorigenic effect of macrophages and attenuating the anti-tumor effect of killer cells such as B cells, CD8+ T cells and CD4+ T cells." (PMID 34607313, 2021).
tumor (continued). "Therefore, we harvested tumors and spleens from BALB/cJ mice before the first treatment and we looked at the expression of PD-1, PD-L1, TIM-3, and LAG-3 on CD4 and CD8 effector lymphocytes in the spleen as well as on tumor infiltrating lymphocytes (TILs)." (PMID 33466653, 2021). "While NK and CD4+ T cells depletions prevented HEI3090 treatment from inhibiting tumor growth, CD8+ T cells depletion had no impact on HEI3090 treatment efficacy." (PMID 33510147, 2021). "As speculated, compared with the vehicle group, the distribution of CD3+, CD4+ and CD8+ T cells in the tumor were slightly enhanced after ICG@PM@NP treatment." (PMID 34794446, 2021). "Tumor tissues with high expression of CCNF showed high immune infiltration, and the expression of CCNF was partially positively correlated with tumor-infiltrating CD4+ T cells, CD8+ T cells, B cells, macrophages, neutrophils, and dendritic cells." (PMID 34397798, 2021). "Infused into the patient, it induces CD4+ and CD8+ immune cells against the tumor antigen." (PMID 33106940, 2021). "Further exploration of the tumor microenvironment has uncovered a correlation between the pattern of Mφ IL-36γ expression and two positive prognostic markers for CRC which comprise CD4+ central memory T-cell infiltration and augmented density of B cells in tertiary lymphoid structures." (PMID 34281268, 2021). "Roberto S. Accolla and colleagues revealed that immune cells including CD4+ T cells, CD8+ T cells, dendritic cells and macrophages would be rapidly infiltrated into tumor cells that were stably transfected with CIITA and had expression of MHC class II molecules." (PMID 34040608, 2021). "Treatment of LLC-OVA tumor-bearing mice with Nb-Fc1B (treatment schedule) resulted in the complete depletion of CCR8+ Tregs in the TME, whereas CD4+Foxp3− T cells remained unaffected." (PMID 33589525, 2021). "On day 60 after the adoptive transfer, tumor rejection was observed in 40% of recipient mice with CD8+ T cells from MBTA-treated mice (2 from 6 mice), 100% of recipient mice with CD4+ T cells from MBTA-treated mice, and in 20% of both control groups with CD4+ or CD8+ T cells." (PMID 34439097, 2021). "There was an expansion of OVA-specific CD4 but not CD8 T cells in the tumor-draining lymph nodes and spleen with huFLT3L treatment." (PMID 34083417, 2021). "Normally, CD4+ Th cells do not directly demolish malignant tumor cells, but they support the development of tumor immunity by recognizing tumor antigen peptides presented by MHC class II molecules and amplifying the activation and clonal expansion of CTL." (PMID 34682791, 2021). "Single-cell transcriptome analysis revealed that tumor-infiltrating CD4+ TC and blood-derived MAMI-IFNγ+Teff accumulate into two distinct clusters, suggesting that their functional profile is affected by the tumor microenvironment." (PMID 33602930, 2021). "We show that iDCs incubated with CM from non-irradiated and irradiated CAFs or A549 tumor cells were not able to induce CD4+ T cell proliferation to the extent of mature DC controls." (PMID 34177901, 2021). "Subsequently, we explored the correlations between LTA and the immune cells in TIMER, its expression was positively correlated with six types of immune cells after adjustment by tumor purity in the TIMER database, namely, B cell, CD8+ T cell, CD4+ T cell, macrophage, neutrophil, and dendritic cell." (PMID 35155447, 2021). "Therefore, the proportions of NK cells, and CD4+ and CD8+ T cells in spleens and tumours were analysed by flow cytometry or immunofluorescence staining." (PMID 33506637, 2021). "In terms of tumor immune cell infiltration, whether in TCGA group or the ICI treatment group, the differences in T.cell.CD8.positive, T.cell.CD4.activated, and Macrophage.M0 were statistically significant." (PMID 33816497, 2021).
tumor (continued). "Treatment was shown to result in a significant reduction in CD8 T cell infiltration into tumours, but not CD4 T cell or γδ T cell infiltration, which corresponds with our earlier observation of the key role played by CD8 T cells in SCC rejection." (PMID 33925140, 2021). "Pro- or anti-tumor dichotomy has also been applied to DCs, since conventional DC 1(CDC1) may cross-present tumor antigens to CD8 T cells with tumor-killing potential, and CDC2 stimulate CD4 T cells that could promote or impede anti-tumor responses." (PMID 34680397, 2021). "There was a significant increase in the expression of OX40 on tumor-infiltrating CD8+ T cells and dendritic cells (DCs) following PL1-OX40 treatment, but there were minimal changes in the OX40 expression on infiltrating CD4+ T cells or macrophages." (PMID 34907171, 2021). "Such nano-vaccines, co-delivering pathogen- or tumor-specific antigen and adjuvant, may address on one hand especially cDC2 via CR3, which at activated state stimulate antigen-specific CD4+ Th and CD8+ T cells." (PMID 33799879, 2021). "Animal studies identified tumor-induced conversion of CD4+ non-Tregs into Tregs as an important mechanism of immune escape and, accordingly, circulating tumor-antigen-specific Tregs can be detected in cancer patients but not in healthy individuals." (PMID 35097027, 2021). "Combination radiation and immune checkpoint blockade modestly shifted the immune profile of orthotopic tumours but did not increase CD4+ or CD8+ T cells to the frequencies observed in subcutaneous tumours." (PMID 34784792, 2021). "In contrast, CD4+ T cells have not received as much attention, although mouse studies have revealed the central role of tumor-specific CD4+ T cells in antitumor immunity." (PMID 34868011, 2021). "Besides, BTH-1677 can inhibit the suppressive activity of Tregs on CD4+ T cells and is able, when treated with whole blood, to enhance CD4+ and CD8+ T cell proliferation, also by driving T cell polarization towards anti-tumor Th1 phenotype." (PMID 36046144, 2021). "In addition, on day 4 of post-treatment, approximately 6% of CD4+ T cells and 11% of CD8+ T cells of total lymphocytes produced IFN-γ in response to co-culture with H11 tumor cells." (PMID 35008305, 2021). "At the same time, the percentage of CD4 CTLs (CD4+Thpok−) and the expression of the CTL cytokine Granzyme B in CD4+ T cells were notably increased after RFA and cryo-thermal therapy compared to that in tumor-bearing mice." (PMID 34576115, 2021). "We found that Class 2, which had a higher fraction of anti-tumor cells such as CD8+ T cells and activated CD4+ memory T cells, had a better prognosis compared to Class 1, which had comparable stromal scores and fractions of immunosuppressive cells, such as Treg cells and M2 macrophages." (PMID 34012914, 2021). "In addition to activated CD4+ and CD8+ T cells, CTLA-4 is constitutively expressed on immunosuppressive FoxP3+ Tregs and plays a crucial role in Treg-driven suppression of anti-tumour immunity." (PMID 34299373, 2021). "In a second step, immunogenicity of identified epitopes is verified through T cell restimulation assays of peripheral blood mononuclear cells from the sequenced patient or MHC-I and -II tetramers or multimers detecting tumor-neoantigen-specific CD8+ and CD4+ T cells, respectively." (PMID 35097027, 2021). "In contrast, there were fewer CD103+CD4+ T cells from both tumor and non-cancerous and tissues than CD103-CD4+ T cells, comprising less than 10% of the total population of CD4+ T cells at both sites." (PMID 33968059, 2021). "In addition, Th1 cells among CD4+ T cells can activate CD8+ cytotoxic T lymphocytes (CTLs), thus stimulating the immune system to suppress tumor progression." (PMID 34367978, 2021). "The action of CM-MSNs may be related to the increase in the number of CD4+ and CD8+ T lymphocytes infiltrating the tumor tissues, which was further enhanced by co-treatment with anti-PD1." (PMID 34834226, 2021).